ABCC10 (ATP binding cassette subfamily C member 10)
Description:
ATP-dependent transporter of the ATP-binding cassette (ABC) family that actively extrudes physiological compounds, and xenobiotics from cells. Lipophilic anion transporter that mediates ATP-dependent transport of glucuronide conjugates such as estradiol-17-beta-o-glucuronide and GSH conjugates such as leukotriene C4 (LTC4). May regulate the transport of organic compounds in testes across the blood-testis-barrier (Probable). Mediates intercellular propagation of antiviral immune signaling in early stages of infection (By similarity). In RNA virus-infected cells, oligoadenylate synthase senses viral dsRNA and generates 2',5'-oligoadenylates (2-5A) which act as second messengers to activate RNASEL and type I interferon signaling to inhibit viral replication (By similarity). This innate signaling pathway is locally extended and amplified by ABCC10, which exports 2-5A from virus-infected cells to cross-activates RNASEL in uninfected neighboring cells and confers protection against viral infection (By similarity). Mediates multidrug resistance (MDR) in cancer cells by preventing the intracellular accumulation of certain antitumor drugs, such as, docetaxel and paclitaxel. Does not transport glycocholic acid, taurocholic acid, MTX, folic acid, cAMP, or cGMP.
Synonyms: MRP7; SIMRP7; EST182763
Tractability: Small molecule: it belongs to a druggable protein family. Antibody: UniProt places it where antibodies can reach, with high confidence; its Gene Ontology location is reachable by antibodies, with high confidence; UniProt predicts a signal peptide or a membrane-spanning region. PROTAC: ubiquitination databases record sites on it.
Target class: ABCC subfamily; ATP-binding cassette; Transporter; Primary active transporter
Safety:
Unwanted effects reported when the protein is acted on. In parentheses: how it was acted on, where the effect was seen, and who reports it.
kidney tubular dysfunction (source: ClinPGx)
nephrotoxicity (source: ClinPGx)
Gene: Protein-coding gene on chromosome 6 (43,427,366 to 43,450,430, forward strand). Ensembl gene ENSG00000124574.
Subcellular location: Cell membrane; Basolateral cell membrane; Basal cell membrane
Pathways (Reactome):
Transport of small molecules: ABC-family protein mediated transport
Gene Ontology:
Molecular function: ABC-type glutathione S-conjugate transporter activity; ABC-type transporter activity; ABC-type xenobiotic transporter activity; ATPase-coupled transmembrane transporter activity; ATP binding; ATP hydrolysis activity; xenobiotic transmembrane transporter activity
Biological process: leukotriene metabolic process; leukotriene transport; transmembrane transport; xenobiotic transport
Cellular component: basal plasma membrane; basolateral plasma membrane; lysosomal membrane; plasma membrane; membrane
Genetic constraint (gnomAD): Loss-of-function variants: 114 observed, 148.99 expected, observed/expected ratio (o/e) 0.77, 90% interval 0.66 to 0.89. The upper end of that interval is the gene's LOEUF score, 0.89, which puts it in group 3 of 6, group 1 being the genes least tolerant of losing a copy. Missense variants: 1,700 observed, 1,969.9 expected, observed/expected ratio (o/e) 0.86, 90% interval 0.83 to 0.9. Synonymous variants: 805 observed, 883.77 expected, observed/expected ratio (o/e) 0.91, 90% interval 0.86 to 0.96.
Homologues: Orthologues: chimpanzee ABCC10 (99% identical), macaque ABCC10 (97% identical), pig ABCC10 (90% identical), dog ABCC10 (89% identical), rat Abcc10 (85% identical), mouse Abcc10 (85% identical), guinea pig ABCC10 (84% identical), rabbit ABCC10 (77% identical), tropical clawed frog abcc10 (56% identical), zebrafish abcc10 (53% identical), Drosophila melanogaster MRP (34% identical), zebrafish abcc6a (32% identical), and 15 more. Paralogues in human: ABCC3 (33% identical), ABCC1 (32% identical), ABCC2 (31% identical), ABCC6 (30% identical), ABCC5 (29% identical), ABCC4 (29% identical), ABCC8 (28% identical), ABCC9 (28% identical), ABCC12 (26% identical), ABCC11 (25% identical), CFTR (22% identical).
Diseases named in the same sentence as ABCC10 in open-access papers:
ABCC10 is named in the same sentence as 37 diseases in open-access papers, as found by Europe PMC text mining. Sharing a sentence is not in itself a finding about the gene and the disease. The quoted sentences say what the papers report.
non-small cell lung carcinoma (8 papers, 2014 to 2026). A group of at least three distinct histological types of lung cancer, including non-small cell squamous cell carcinoma, adenocarcinoma, and large cell carcinoma. "Clinically, a significantly high level of ABCC10 expression has been found in non-small cell lung cancer and acute myeloid leukemia after chemotherapy, causing acquired resistance." (PMID 25268163, 2014). "It has been found that ABCC10 has associations with vinorelbine and paclitaxel resistance in non-small cell lung cancer." (PMID 25268163, 2014). "The m6A modification was significantly enriched upon ABCC10 gene expression in drug-resistant non-small cell lung cancer." (PMID 36585626, 2022). "Although ABCC10 was shown to be highly expressed in non-small cell lung cancer cells and serves as a predictive marker for multi-drug resistance, our results show that it can be further elevated by cancer cell exposure to an alkylating drug—cisplatin." (PMID 35205642, 2022). "ABCC10 has been reported to confer resistance to vinorelbine and paclitaxel in non-small cell lung cancer and salivary gland adenocarcinoma." (PMID 28051999, 2017). "In addition, ABCC10 was also reported to involve in the chemotherapeutic resistance in some types of cancer, including non-small cell lung cancer and ovarian cancer." (PMID 33593355, 2021).
breast carcinoma (7 papers, 2018 to 2026). "A similar profile of changes was observed in breast cancer cells transfected with siBRD, where only the highly transcribed ABCC10 responded to BRD deficiency, with further transcription enhancement." (PMID 34572840, 2021). "Studies have reported that ABCB5, ABCB8, ABCB10, ABCC2–5, and ABCC10 are overexpressed in breast cancer cells or are associated with breast cancer progression." (PMID 30202239, 2018). "To further investigate the relationship between ABCC10 and RT outcomes, we analyzed survival data from The Cancer Genome Atlas (TCGA) for breast cancer, head, and neck cancer, and pancreatic cancer." (PMID 40770563, 2026). "Additional members of this family include ABCC3 functioning in breast cancer and ABCC10 (MRP7) providing paclitaxel resistance in NSCLC." (PMID 33918653, 2021). "In the studied MDA-MB-231 breast cancer cells, the transient silencing of BRD2/3/4 and bromodomain inhibition caused a significant increase in the mRNA of ABCC10, which is the most abundant MDR protein in this cell line." (PMID 34572840, 2021). "The addition of MRP7 (ABCC10 gene) to the MRP subfamily was reported in 2001, to which was also later added MRP8 (ABCC11 gene) and MRP9 (ABCC12 gene); these last two are greatly expressed in breast cancer." (PMID 37092502, 2023). "Non-resistant breast cancer cells augmented the expression of ABCC10, but not ABCC4, after their incubation with a single dose of cisplatin." (PMID 35205642, 2022).
colorectal cancer (5 papers, 2017 to 2022). A primary or metastatic malignant neoplasm that affects the colon or rectum. "ABCC10 has genetic variants that have been shown to contribute to variability in the plasma concentration of anti-viral drugs or response to oxaliplatin in colorectal cancer." (PMID 30890141, 2019). "In contrast to our findings, genetic variability in ABCC10 (rs2125739) has been associated with survival outcome in colorectal cancer patients receiving oxaliplatin-based chemotherapy." (PMID 30890141, 2019). "Consistent with our finding that FOXM1 has a vital role in 5-FU resistance, a recent study has shown that FOXM1 can enhance 5-FU resistance through promoting the efflux of antitumour drugs by up-regulating the ABC subfamily C member 10 (ABCC10) expression in colorectal cancer cells." (PMID 30728402, 2019).
lung cancer (3 papers, 2019 to 2022). A malignant neoplasm involving the lung. "Notably, exosomal-FTO facilitated ABCC10 of recipient cells via FTO/YTHDF2/ABCC10 axis, eventually leading to gefitinib resistance in non–small cell lung cancer (NSCLC)." (PMID 36517820, 2022).
atherosclerosis (2 papers, 2022). A disease characterized by the build-up of fatty material and calcium deposition in the arterial wall resulting in partial or complete occlusion of the arterial lumen. "Since changes in lipid levels are associated with the development of atherosclerosis, and bioinformatics analysis of genes expressed in samples of atherosclerotic lesions has been shown to increase the expression of ABCC10, we wanted to see if ABCC10 deficiency affects atherosclerosis." (PMID 36430292, 2022). "A bioinformatics analysis of genes expressed in samples of atherosclerotic lesions and control arteries without atherosclerotic lesions showed an increased expression of ABCC10 in lesion areas suggesting a role of ABCC10 in atherosclerosis." (PMID 36297086, 2022). "Unexpectedly, ABCC10 deficiency does not affect triglyceride levels or atherosclerosis in ApoE-deficient mice." (PMID 36430292, 2022). "In this study, we aimed to investigate the impact of ABCC10 deletion on lipids and lipoprotein metabolism in relation to obesity and atherosclerosis, with the understanding that this knowledge might help to devise new strategies to control hyperlipidemia." (PMID 36430292, 2022). "We also did not see any significant difference in the extent of plaques or en face staining with Oil Red O in thoracic aortic areas between Apoe−/− and Abcc10−/−, Apoe−/− double-knockout mice, suggesting that ABCC10 deficiency does not affect atherosclerosis." (PMID 36430292, 2022). "Therefore, we hypothesized that lower hyperlipidemia and the absence of ABCC10 in Abcc10−/− mice might reduce atherosclerosis in Apoe−/− mice." (PMID 36430292, 2022). "Therefore, changes in ABCC10 levels in our study may not have had any direct biochemical effect on the development of atherosclerosis in mice." (PMID 36430292, 2022).
bladder cancer (2 papers, 2018 to 2023). "The roles of ABCC5, ABCA8, ABCC10, ABCB10, ABCG1, ATP7B, ABCG2, and mitochondrial SLC25A10 in platinum-receiving urinary bladder cancer patients should be the subject of further investigation." (PMID 36650399, 2023).
hepatocellular carcinoma (2 papers, 2018 to 2022). A malignant tumor that arises from hepatocytes. "In summary, we identified a novel role of ABCC10 in the biosynthesis and efflux of HexCer in human hepatoma cells." (PMID 36297086, 2022). "Expression of ABCC10 is elevated in hepatocellular carcinoma compared with adjacent healthy liver tissue." (PMID 36297086, 2022). "An example of this regulation is how let-7a and let-7e modulate the gene ABCC10 in some cancers like hepatocellular carcinomas." (PMID 30255799, 2018). "Using an unbiased knockdown approach, we found that ATP-binding cassette transporter protein C10 (ABCC10) participates in the synthesis of HexCer and thereby affects egress to HDL in human hepatoma Huh-7 cells." (PMID 36297086, 2022).
leukaemia (2 papers, 2023 to 2024). "Notably, similar to the role of ABCC5 and ABCC10 in modulating proliferation and apoptosis in leukaemia, ABCE1 knockdown significantly suppressed H69/ADR cell growth, augmented the cell cycle inhibition rate, and promoted apoptosis." (PMID 39679367, 2024). "The most contemplative case in ABC transporter-related chemoresistance may affiliated with ABCC5 and ABCC10, where they exhibited antiapoptotic and proliferative properties except for the drug efflux ability in leukemia doxorubicin resistance cells." (PMID 39679367, 2024). "miRNAs have the utmost importance in overcoming chemoresistance in leukaemia by targeting ABC transporters like P-gp and others, such as ABCE1, ABCC5, and ABCC10." (PMID 39679367, 2024). "Even though in most tumorigenesis and doxorubicin drug resistance, P-gp is the pioneer reprehensive of ABC transporters targeted by miRNAs, in leukaemia, some other little-known members comprising of ABCE1, ABCC5, and ABCC10 have been inferred in this process." (PMID 39679367, 2024).
neuroblastoma (2 papers, 2018 to 2025). Neuroblastoma (NB) is the most common solid, extracranial childhood tumor. "Further analysis of the regulation between PHLDA1 and efflux pumps (such as ABCB1and ABCC10) is needed in other neuroblastoma cell lines and for treatment with different cytotoxic drugs to establish whether this mechanism operates more broadly." (PMID 41430389, 2025).
Obesity (2 papers, 2022). Accumulation of substantial excess body fat. "In summary, these studies show that ABCC10 deficiency ameliorates diet-induced obesity in mice." (PMID 36430292, 2022). "Abcc10 gene knockout mice appear normal on a regular chow diet but are protected from high-fat-diet-induced obesity similarly to Mgat2 and Park2 knockout mice, and their plasma triglyceride levels are also decreased." (PMID 36430292, 2022). "We fed Abcc10+/+ and Abcc10−/− mice with a high-fat diet for 16 weeks to induce obesity and measured the body weight every two weeks." (PMID 36430292, 2022). "As expected, there was a significant increase in body weight in high-fat obesity-diet-fed Abcc10+/+ (HFD-Abcc10+/+) mice over the period of 16 weeks as compared to chow-fed Abcc10+/+ (CD-Abcc10+/+) mice." (PMID 36430292, 2022). "Deletion of the Abcc10 gene also alters several lipid metabolism genes in the intestine, suggesting that ABCC10 regulates dietary fat absorption, which may contribute to diet-induced obesity in mice." (PMID 36430292, 2022). "Furthermore, deletion of ABCC10 ameliorates diet-induced obesity in mice and leads to a better response during insulin and glucose tolerance tests." (PMID 36430292, 2022). "Similarly, we observed an increase in the body weight in high-fat obesity-diet-fed Abcc10−/− (HFD-Abcc10−/−) mice compared to CD-Abcc10+/+ mice, but this increase was lower than in the HFD-Abcc10+/+ mice." (PMID 36430292, 2022). "The results confirm ABCC10 role in the prevention of dyslipidemia and obesity." (PMID 36601507, 2022). "It is likely that agents that inhibit the activity of ABCC10 might reduce hyperlipidemia and obesity." (PMID 36430292, 2022).
Anxiety (1 paper, 2012). Intense feelings of nervousness, tension, or panic often arise in response to interpersonal stresses. "Furthermore, assessment of activity, exploratory behavior, and anxiety levels revealed behavioral alterations in ABCB10/0 and ABCC10/0 mice, whereas ABCG20/0 mice were mostly unaffected." (PMID 22545122, 2012). "Therefore, ABCC10/0 mice kept a normal phenotype under non-stress conditions, but intensified anxiety in the light area (stress)." (PMID 22545122, 2012).
diabetes (1 paper, 2022). "To investigate whether ABCC10 deficiency has any effect on the development of diabetes during high-fat-diet feeding in mice, we measured the levels of plasma glucose every two weeks." (PMID 36430292, 2022).
dyslipidemia (1 paper, 2022). "Additionally, ABCC10 mediates multidrug resistance in cancer cells; dyslipidemia may contribute to multidrug resistance in cancer cells via ABCC10 up-regulation." (PMID 36601507, 2022).
HIV-1 infection (1 paper, 2019). The type species of lentivirus and the etiologic agent of acquired immunodeficiency syndrome (AIDS). "This hypothesis is consistent with the observation that the rs2125739 polymorphism is significantly associated with the plasma concentration of nevirapine, a non-nucleoside reverse transcriptase inhibitor for HIV-1 infection that is also a substrate for ABCC10/MRP7." (PMID 30890141, 2019).
Insulin resistance (1 paper, 2022). Increased resistance towards insulin, that is, diminished effectiveness of insulin in reducing blood glucose levels. "Similar observations were made in Park2 gene knockout mice, which support our data suggesting that impaired intestinal lipid absorption in ABCC10 knockout mice may reduce the metabolic load to peripheral organs and, therefore, protects the mice from high-fat-diet-induced insulin resistance." (PMID 36430292, 2022).
myeloid leukemia (1 paper, 2012). A clonal proliferation of myeloid cells and their precursors in the bone marrow, peripheral blood, and spleen. "Additionally, detection of ABCA2, ABCB2 and ABCC10, which were found overexpressed in childhood AML, may be worthy to build the gene regulation network in proliferation of myeloid leukemia cells." (PMID 23067006, 2012).
neutropenia (1 paper, 2019). A decrease in the number of neutrophils found in the blood. "Our results indicate that genetic variation in the ABCC10 gene is associated with neutropenia for docetaxel treatment." (PMID 30890141, 2019). "In contrast, ABCC10 knockout mice treated with paclitaxel exhibited increased lethality associated with neutropenia and marked bone marrow toxicity." (PMID 30890141, 2019). "Further prospective studies of the relationship between the ABCC10 genotype and the incidence of neutropenia and/or neutropenic fever following docetaxel treatment are now warranted." (PMID 30890141, 2019). "In this study, we found that genetic variation within the ABCC10 gene is associated with docetaxel cytotoxicity in NSCLC cell lines and CRISPR edited cells, and with neutropenia in NSCLC patients treated with this drug." (PMID 30890141, 2019). "However, the finding suggests that ABCC10 may play a more important role than other transporters, since this was the only gene which was associated with both in vitro docetaxel cytotoxicity and clinical neutropenia in this study." (PMID 30890141, 2019). "Although we did not examine the pharmacokinetics of docetaxel in this study, these data suggest that genetic variation in ABCC10 may influence the pharmacokinetics of docetaxel, resulting in the observed relationship with grade 3/4 neutropenia and/or neutropenic fever." (PMID 30890141, 2019).
pancreatic cancers (1 paper, 2026). "ABCC10 expression is widely detected in various cancers, including breast, lung, ovarian, and pancreatic cancers." (PMID 40770563, 2026).
rheumatoid arthritis (1 paper, 2022). A chronic, systemic autoimmune disorder characterized by inflammation in the synovial membranes and articular surfaces. "ABCC10 expression is significantly higher in monocyte-derived macrophages and peripheral blood lymphocytes obtained from rheumatoid arthritis patients." (PMID 36297086, 2022).
triple-negative breast carcinoma (1 paper, 2022). An invasive breast carcinoma which is negative for expression of estrogen receptor (ER), progesterone receptor (PR), and human epidermal growth factor receptor 2 (HER2). "Acetyltransferase is responsible for higher ABCC10 expression in cisplatin-resistant non-small cell lung and triple-negative breast cancer cell lines." (PMID 35205642, 2022). "The other CoREST complex member, LSD1, was reported to repress ABCC1 and ABCC10 gene expression upon inhibition of EP300 in the triple-negative breast cancer cell line MDA-MB-231." (PMID 35205642, 2022).